IFIT3 (interferon induced protein with tetratricopeptide repeats 3)
Diseases named in the same sentence as IFIT3 in open-access papers (continued):
Sharing a sentence is not in itself a finding about the gene and the disease.
acute myeloid leukemia (2 papers, 2025). Acute myeloid leukemia (AML) is a group of neoplasms arising from precursor cells committed to the myeloid cell-line differentiation. "IFIT1, IFIT2, IFIT3, and IFIT5 are overexpressed in acute myeloid leukemia (AML) patients, with higher levels of IFIT2, IFIT3, and IFIT5 predicting poor prognosis." (PMID 41048997, 2025).
cervical carcinoma (2 papers, 2023). A carcinoma arising from either the exocervical squamous epithelium or the endocervical glandular epithelium. "IFITs suppress RSV infection in human cervical carcinoma cells as shown by overexpression of IFIT1, IFIT2 or IFIT3 individually." (PMID 37515100, 2023). "COL8A1 has been shown to promote non-small cell lung cancer progression by activating IFIT1/IFIT3-mediated EGFR signaling, while FABP5 can promote lymph node metastasis in cervical cancer by reprogramming fatty acid metabolism." (PMID 37795080, 2023).
cognitive decline (2 papers, 2021 to 2023). "Interestingly, the interferon-responsive gene Ifit3, which is reported to be involved in cognitive decline in aged mice, was specifically upregulated in the hippocampus of H7N7-infected mice and is expressed mainly in granule cells." (PMID 34585989, 2021).
colon cancer (2 papers, 2024). "In colon cancer cells (i.e., HT29 and HCT116), IFIT3 expression was downregulated under treatment with the anti-programmed cell death-1 (anti-PD-1) antibody nivolumab." (PMID 38200280, 2024). "We selected eight representative immune-related molecules for qPCR validation in SW480 and another colon cancer cell line HT29: DDX58, CHST4, TNFSF18, XAF1, OAS1, IFI27, IFI44, IFIT3." (PMID 38281029, 2024). "DDX58, XAF1, OAS1, IFI27, IFI44 or IFIT3 was indeed downregulated and CHST4 or TNFSF18 was upregulated in MDM4 overexpressed colon cancer cells." (PMID 38281029, 2024).
colorectal cancer (2 papers, 2024). A primary or metastatic malignant neoplasm that affects the colon or rectum. "To create an endogenous type I IFN reporter, we chose the colorectal cancer cell line HCT116, which is highly efficient for CRISPR-based gene editing, and surveyed IFNα induction of canonical type I IFN target genes (IFIT1, IFIT2, IFIT3, IFI27, IRF7, OASL, RSAD2)." (PMID 38358346, 2024).
esophageal cancer (2 papers, 2018 to 2024). A primary or metastatic malignant neoplasm involving the esophagus. "Interestingly, the proteomic study on esophageal cancer also noted that the immune response genes that they identified as differentially expressed (MX1, IDO1, IFIT1, and IFIT3) did not correspond to alterations in published genomic data." (PMID 39285636, 2024).
gastric adenocarcinoma (2 papers, 2024). "To decipher the cellular state and function of macrophages in the process of intestinal-type gastric adenocarcinoma carcinogenesis, we reclustered all of the macrophages into five clusters, including macrophage_IL1B, macrophage_CHI3L1, macrophage_CXCL3, macrophage_IFIT3 and macrophage_FOLR2." (PMID 39702278, 2024).
gastric cancer (2 papers, 2019 to 2022). A primary or metastatic malignant neoplasm involving the stomach. "The distributions of SNVs from the TCGA-STAD cohort showed that altered frequencies of STAT1 and IFIT3 came first and third among 48 gastric cancer patients." (PMID 36311733, 2022). "For HER2+ gastric cancer, the high expression of VIM, IFI44, IFI44L, IFIT2, IFIT3, ISG15, OAS1, or OASL was associated with worse overall survival (P < 0.05)." (PMID 31949544, 2019).
head and neck squamous cell carcinoma (2 papers, 2024 to 2025). A squamous cell carcinoma that arises from any of the following anatomic sites: lip and oral cavity, nasal cavity, paranasal sinuses, pharynx, larynx, and salivary glands. "Moreover, IFIT3 is overexpressed in head and neck squamous cell carcinoma, where it activates the PI3K/AKT pathway by targeting PD-L1, thereby promoting proliferation, migration, and invasion." (PMID 40463715, 2025).
hepatitis B virus infection (2 papers, 2022 to 2024). A viral infection caused by the hepatitis B virus. "Interestingly, IFIT3 has been found to enhance the antiviral effect of IFN-α through the JAK-STAT pathway, concurrently impeding cell proliferation in hepatitis B virus infection." (PMID 39664492, 2024).
myocardial infarction (2 papers, 2021 to 2024). Gross necrosis of the myocardium, as a result of interruption of the blood supply to the area, as in coronary thrombosis. "Although the role of Ifit3 in cardiac biology is uncertain, very recently, it was reported that downregulation of Ifit3 relieved the inflammatory response and myocardial fibrosis of mice with myocardial infarction and improved their cardiac function." (PMID 39285385, 2024). "IFIT2, IFIT3 and IFI44L are significantly related with myocardial infarction and coronary artery disease, according to Cardiovascular Disease Knowledge Portal Project Database (cvd.hugeamp.org)." (PMID 34884921, 2021).
non-small cell lung carcinoma (2 papers, 2023 to 2025). A group of at least three distinct histological types of lung cancer, including non-small cell squamous cell carcinoma, adenocarcinoma, and large cell carcinoma. "Strong evidence indicates that IFIT3 plays a pivotal role in regulating PD-L1 expression in cancers such as non-small cell lung cancer (NSCLC) and head and neck cancer (HNC)." (PMID 40061935, 2025).
primary biliary cholangitis (2 papers, 2021 to 2024). Primary biliary cholangitis (PBC) is a chronic and slowly progressive cholestatic liver disease of autoimmune etiology characterized by injury of the intrahepatic bile ducts that may eventually lead to liver failure. "In senescent biliary epithelial cells, Overexpression of IFIT3 was found, and it may be connected to the etiology of primary biliary cholangitis." (PMID 38484366, 2024).
thyroid cancer (2 papers, 2021 to 2025). "Although we have not found any report about how IFIT3 works in cancer, based on the significant association of IFIT3 and prognosis of thyroid cancer patients, we think its insight should be further studied." (PMID 33711033, 2021). "However, the stable mutation status of RPS27L and IFIT3 together with their high expression in tumor tissues makes them potential biomarkers as well as therapeutic targets in thyroid cancer." (PMID 33711033, 2021). "In addition, our study of IFIT3 implies its great potential in thyroid cancer progressing which has not been reported yet, and these RBPs especially RPS27L and IFIT3 may also be used in clinical adjuvant therapy." (PMID 33711033, 2021).
amyloid (1 paper, 2021). "In a previous study, we proposed that Ifit3 might physically interact with App, making its aggregation in amyloid plaques plausible." (PMID 34702310, 2021).
anorexia nervosa (1 paper, 2020). A disorder most often seen in adolescent females characterized by a refusal to maintain a minimally normal body weight, an intense fear of gaining weight, a disturbance in body image, and, in postmenarcheal females, the development of amenorrhea. "Across the four anorexia nervosa associated gene sets, four genes overlap between the Lutter damaging variants and Negraes iPSC derived gene set (TNFRSF10A, SCGB1A1, IFIT3, and GIPC3; hypergeometric test, p < 0.02)." (PMID 32651428, 2020).
central nervous system lymphoma (1 paper, 2025). "Based on in silico analysis of primary central nervous system lymphoma (PCNSL) patients’ data, high IFIT3 gene expression was reported to be associated with better patient prognosis." (PMID 40564154, 2025).
cholangiocarcinoma (1 paper, 2024). A carcinoma that arises from the intrahepatic biliary tree (intrahepatic cholangiocarcinoma) or from the junction, or adjacent to the junction, of the right and left hepatic ducts (hilar cholangiocarcinoma). "We analyzed the expression levels of Type I interferons and ISG genes in the tumor tissues of patients and normal control tissues, revealing a consistent upregulation of ISG genes, including ISG15, MX1, MDA5, IFIT2, IFIT3, IRF1 and IRF7, in the tumor tissues of patients with cholangiocarcinoma." (PMID 38817870, 2024).
cholangitis (1 paper, 2021). An acute or chronic inflammatory process affecting the biliary tract. "Significantly increased expression of IFIT3 was seen in senescent BECs in small bile ducts showing cholangitis and in ductular reactions in PBC, compared to control livers (p < 0.01)." (PMID 34075171, 2021). "The expression of IFIT3 was significantly increased in BECs in small bile ducts involved in cholangitis in PBC." (PMID 34075171, 2021). "The expression of IFIT3 was significantly correlated with cholangitis activity in PBC (p < 0.01)." (PMID 34075171, 2021).
chronic hepatitis C (1 paper, 2011). "On the other hand, CXCL9 and IFIT3 were reported to relate to liver fibrosis in chronic hepatitis C patients." (PMID 21886832, 2011).
co-infection (1 paper, 2018). "Moreover, depletion of IFIT3 induced cell death in the U549 human carcinoma cell line, an effect potentiated by co-infection with dengue virus." (PMID 29554348, 2018).
colorectal adenocarcinoma (1 paper, 2017). The most common type of colorectal carcinoma. "However, the expression of IFIT3 was not significantly altered (-1.11-fold, p=0.17 with IFIT3 probe #204747: and -1.23-fold with IFIT3 probe #229450, p=0.12) in colorectal adenocarcinoma, suggesting that other factor(s) may be involved in the regulation of IFIT3 expression in colorectal tumors." (PMID 29245969, 2017).
coronary artery disease (1 paper, 2021). "The most relevant genetic variants of IFIT2 and IFIT3 linked to coronary artery disease are extensively summarized." (PMID 34884921, 2021).
diffuse large B-cell lymphoma (1 paper, 2025). "In another hematological malignancy, diffuse large B-cell lymphoma (DLBCL), decreased gene expression levels of IFIT3 were linked to enhanced immune therapy sensitivity." (PMID 40564154, 2025).
inflammatory skin disease (1 paper, 2021). Inflammatory skin disorders covers a broad category that includes many conditions ranging in severity, from mild itching to grave medical health complications These disorders are common in people of all ages and races. "Likewise, under AZ(−) conditions, THDC increased expression of genes belonging to the STAT1-57 module (P < 0.01), which is a set of genes activated by interferon signaling with elevated expression in inflammatory skin disease (e.g., MX2, IFIT3, IFI44)." (PMID 34445461, 2021).
ischemia (1 paper, 2021). A hypoperfusion of the BLOOD through an organ or tissue caused by a PATHOLOGIC CONSTRICTION or obstruction of its BLOOD VESSELS, or an absence of BLOOD CIRCULATION. "Increased expression of IFIT2, IFIT3 and IFI44L, as well as the ratios of IFIT2/IFIT3 and IFI44L/IFIT3, may boost apoptosis and aggravate ischemia-induced damage." (PMID 34884921, 2021).
large-cell lung carcinoma (1 paper, 2026). "Herein, the clinicopathological significance of IFIT3 expression in lung squamous cell carcinoma (LUSC) and large-cell lung carcinoma (LCLC) specimens was assessed." (PMID 41850400, 2026).
lentivirus infection (1 paper, 2022). Virus diseases caused by the Lentivirus genus. "HepG2 and HL-7702 cells stably overexpressing IFIT3 were also constructed by lentivirus infection." (PMID 36314949, 2022).
leukopenia (1 paper, 2022). "The combination model of MX2 and IFIH1 could determine high-risk patients with leukopenia, and the combination model of IFIT3 and IFIH1 had a definite diagnostic accuracy in detecting fever among patients with SLE." (PMID 35757684, 2022).
lung disease (1 paper, 2021). "By specific lung cell isolation, several interferon-related and autoimmune genes were disproportionately expressed among CIA and CIA+ODE (e.g. Oasl1, Oas2, Ifit3, Gbp2, Ifi44, and Zbp1), corresponding to RA and RA-associated lung disease." (PMID 33577605, 2021).
lung fibrosis (1 paper, 2024). "This study confirmed that IFIT3−/− mice exhibited attenuated skin and lung fibrosis induced by bleomycin." (PMID 39305055, 2024). "Constructed an IFIT3−/− mouse model using clustered regularly interspaced short palindromic repeats (CRISPR)/CRISPR‐associated protein 9 (Cas9) gene editing to assess the potential benefits of intervening in the IFIT3/TBK1 signalling pathway on skin and lung fibrosis in the SSc mouse model." (PMID 39305055, 2024). "However, additional investigations are needed to determine whether overexpression of IFIT3 can directly induce skin and lung fibrosis in mice." (PMID 39305055, 2024). "The IFIT3−/− mouse model shows potential benefits of targeting the IFIT3/TBK1 signalling pathway in reducing skin and lung fibrosis in the SSc mouse model." (PMID 39305055, 2024).
lupus nephritis (1 paper, 2021). Glomerulonephritis in the context of systemic lupus erythematosus. "We found EZH2 was upregulated in renal biopsies from lupus nephritis patients as compared with normal para-carcinoma kidney tissues; and there were significant positive correlations between the expression of EZH2 and CXCL10 or IFIT3, respectively." (PMID 33868295, 2021).
lymphoma (1 paper, 2019). A malignant (clonal) proliferation of B- lymphocytes or T- lymphocytes which involves the lymph nodes, bone marrow and/or extranodal sites. "In lymphoma cells, IFIT3 was reported to inhibit cell proliferation through upregulation of p21 and p2713." (PMID 31164632, 2019).
myeloid leukemia (1 paper, 2021). A clonal proliferation of myeloid cells and their precursors in the bone marrow, peripheral blood, and spleen. "For example, in pro-monocytic myeloid leukemia cells, IFIT3 expression induced G1 phase arrest by increasing the expression of the cyclin-dependent kinase inhibitors, p21 and p27." (PMID 34622927, 2021).
Obesity (1 paper, 2021). Accumulation of substantial excess body fat. "As observed with bulk RNA-sequencing, we observed a global suppression of interferon signaling pathways with pregravid obesity across all clusters as exemplified by reduced expression of interferon-stimulated genes (IFIT3, ISG15, OAS1)." (PMID 34195568, 2021).
parasitic infection (1 paper, 2020). "The upregulation of Ifit3 may be essential to promote the IFN-α induced expression of IFN-γ in the NK cells, and ultimately enhances the host’s functional ability to resist the parasitic infection." (PMID 32731337, 2020).
periodontal diseases (1 paper, 2025). "IFIT3 and MX1 are important mediators of inflammation and vascular diseases and may be involved in the pathogenesis of KD and periodontal diseases." (PMID 40421421, 2025).
prostate carcinoma (1 paper, 2025). A carcinoma that arises from epithelial cells of the prostate gland. "In prostate cancer (PrCa) study, downregulation of the β6 integrin subunit was found to significantly promote IFIT3 expression in PrCa cells and their released small extracellular vesicles (sEVs), suggesting that IFIT3 may be negatively regulated by β6 integrin." (PMID 40061935, 2025).
psoriasis (1 paper, 2024). An autoimmune condition characterized by red, well-delineated plaques with silvery scales that are usually on the extensor surfaces and scalp. "The differential genes, biological processes, and signal pathways of psoriasis, especially information related to and diagnostic efficiency of the IFIT3 gene, were obtained by bioinformatics analysis." (PMID 39239353, 2024). "The present study identifies multiple DEGs associated with psoriasis and highlights the roles of IFIT3 while providing directions for further research on the development and immune mechanisms of psoriasis." (PMID 39239353, 2024). "The IFIT3 gene functions can be verified by subsequent large samples to further identify highly sensitive and specific diagnostic markers as well as provide strong support for the targeted treatment of psoriasis-related diseases." (PMID 39239353, 2024). "More importantly, we substantiated the efficacy of the IFIT3 gene as a diagnostic marker for psoriasis via ROC curve analysis, with the AUC values consistently exceeding 0.97 across the three datasets and demonstrating the exceptionally high diagnostic efficacy." (PMID 39239353, 2024). "The functions and related signal pathways of the IFIT3 gene in the skin lesions of patients with psoriasis were explored through bioinformatics methods to determine the potential specific molecular markers of psoriasis." (PMID 39239353, 2024). "The functional and pathway enrichment analyses of the IFIT3 gene help in further understanding its function in psoriasis." (PMID 39239353, 2024). "IFIT3 was highly expressed in psoriatic lesions and may thus be helpful in the diagnosis of psoriasis." (PMID 39239353, 2024). "In this study, the IFIT3 gene was analyzed through bioinformatics, and it was found that IFIT3 was closely related to psoriasis-related infection and immune pathways as well as cytokines; it showed high expressions in psoriatic lesions and had good identification value." (PMID 39239353, 2024). "The expression level of IFIT3 in the psoriatic lesions was higher than that in NL tissues and had better identification efficacy, further demonstrating the pertinence of IFIT3 in the diagnosis and targeted treatment of psoriasis." (PMID 39239353, 2024). "The high expressions of IFIT3 are significantly enriched in the antiviral response and immune regulation pathways, suggesting that IFIT3 may be involved in the occurrence and progression of psoriasis through modulation of these pathways." (PMID 39239353, 2024). "Therefore, IFIT3 may interfere with psoriasis by related antivirus regulating pathways and induce the production of IFN." (PMID 39239353, 2024).
pulmonary hypertension (1 paper, 2020). Increased pressure within the pulmonary circulation due to lung or heart disorder. "Among these proteins, we selected HMOX1 (or HO-1) and IFIT3 for confirmation by the semi-quantitative Western blot approach to confirm these findings due to the importance of HMOX1 and EIF2AK2 (or PKR) in the pulmonary field and due to the novelty of IFIT3 in the pulmonary hypertension field." (PMID 33036472, 2020).
pulmonary TB (1 paper, 2022). "The top performing single biomarkers for pulmonary TB versus controls were CALCOCO2, SAMD9L, GBP1, IFITM3, IFIT3 and SNX10." (PMID 35720382, 2022).
schizophrenia (1 paper, 2022). A major psychotic disorder characterized by abnormalities in the perception or expression of reality. "We then observed significant overlap (three overlapping genes (IFIT2, IFIT3, and ANXA3; OR = 77.4, P = 7.4e−5) between RP5-998N21.4OE-induced DEGs in SK-N-SH cells and RP5-998N21.4-coexpressed schizophrenia-associated DEGs in twin subjects." (PMID 35232977, 2022). "In conclusion, our findings illustrate an epigenetic mechanism by which upregulation of lncRNA RP5-998N21.4 underlies the development of schizophrenia via the enhancement of IFIT2- and IFIT3-mediated immune defense responses through activation of STAT1 signaling pathways." (PMID 35232977, 2022). "Collectively, these results indicate that RP5-998N21.4 might regulate immune defense-related pathways by promoting the transcription of IFIT2, IFIT3, or ANXA3, which are involved in the pathophysiology of schizophrenia." (PMID 35232977, 2022). "Although our studies demonstrate the involvement of RP5-998N21.4 in the development of schizophrenia through the enhancement of IFIT2- and/or IFIT3-mediated immune defense response pathways, it is currently unclear how RP5-998N21.4 influences synapse morphology and function." (PMID 35232977, 2022).
skin tumors (1 paper, 2025). "Consistently, we observed inflammatory genes, including Ifng, Stat1, Ifit2, Ifit3, Isg15, and Bst2, being highly expressed in the T cell cluster in skin tumors." (PMID 40282557, 2025).
squamous cell carcinoma of the (1 paper, 2024). "However, IFIT3 can also promote tumor progression and metastasis in squamous cell carcinoma of the head and neck." (PMID 38753689, 2024).